IL10 (interleukin 10)
Diseases named in the same sentence as IL10 in open-access papers (continued):
Sharing a sentence is not in itself a finding about the gene and the disease.
colitis (continued). "Despite that IL-10 effectively treats colitis in mouse models and suppresses inflammatory cytokine production in vivo in intestinal cells from IBD patients, in diseases with a relative or absolute IL-10 deficiency, a persistent immune activation still exists." (PMID 23056142, 2012). "Moreover, beneficial effects in colitis patients have been obtained via probiotic bacteria-induced IL-10 production." (PMID 22681958, 2012). "It should be further validate that whether IG would modulate the inflammation in different colitis models such as the IL-10 knock-out model and therapeutic trails for established colitis." (PMID 21931839, 2011). "Furthermore, M. Kronenberg and his colleagues recently found that IL-10 secreted by other cells is needed for T reg cells to sustain expression of Foxp3 and prevent colitis." (PMID 21533081, 2011). "Studies using mice in a Trinitrobenzene Sulfonic Acid (TSA) induced colitis model, treated with Vitamin D and dexamethasone, show that the combined use of Vitamin D and dexamethasone enhanced Foxp3 expression accompanied by the induction of IL-10 and TGF-beta." (PMID 21829599, 2011). "IL-10 production by Foxp3+ T reg cells is required for the prevention of colitis." (PMID 21533081, 2011). "In order to investigate the effect of W-061 on these T cells, we utilized a DSS-induced mice colitis model which does not exhibit any immune disorder, in contrast to IL-10 deficient mice." (PMID 21931623, 2011). "In the gut, CO has been found to ameliorate colitis by the induction of IL10 via HO-1 and may be the route by which aminosalicylate drugs have their effect." (PMID 21931826, 2011). "Since IL-10 is a potent anti-inflammatory cytokine, and several in vivo studies have shown its protective role in a variety of pathological states (e.g. colitis, hepatic ischemia/reperfusion and myocardial ischemia/reperfusion), a reduced production due to bIAP treatment would not be favorable." (PMID 28357012, 2011). "The specific deletion of IL-10 in Foxp3+ T reg cells in mice induces inflammation especially in the intestine, indicating that IL-10 derived from T reg cells plays a critical role in controlling colitis." (PMID 21533081, 2011). "It is well documented that commensals have the potential to trigger and perpetuate intestinal inflammation in various spontaneous colitis models like IL-10 deficient mice which do not develop colitis when kept under germ-free conditions." (PMID 21188217, 2010). "In addition, the colitis and colitis-associated colorectal tumors (CAC) spontaneously generated in IL10−/− mice can be ameliorated if mice are kept in germ-free conditions or concurrently ablated of TLR4." (PMID 20885960, 2010). "PPARα might be one of the key mediators in these signaling processes before and after colitis onset in Il10−/− mice." (PMID 20671959, 2010). "Two recent studies showed independently that TLR4 may not be the culprit in the pathogenesis of commensal-dependent colitis in IL-10−/− mice." (PMID 20803699, 2010). "Based on these studies, the second hypothesis was that PPARα and IL10 signaling pathways are interlinked during colitis." (PMID 20671959, 2010). "The timeline of colitis development is unknown in these bacterially inoculated Il10−/− (C57BL/6J) mice." (PMID 20671959, 2010). "The ability of different lactobacilli to induce a high ratio of IL-10/IL-12 production in human peripheral blood mononuclear cells (PBMCs) has been shown to correlate with their capacity to provide significant protection from TNBS induced colitis in mice." (PMID 20498715, 2010). "Bacterial inoculation resulted in severe colitis in Il10−/− mice from 10 to 12 weeks of age." (PMID 20671959, 2010). "Accordingly, mice lacking il10 or harbouring Stat3-deficient macrophages are characterized by excessive cytokine release and develop colitis." (PMID 20478049, 2010).
colitis (continued). "Gene expression changes in 12-week-old Il10−/− mice were related to PPARα signaling likely to control colitis, but how PPARα activation might regulate intestinal IL10 production remains to be determined." (PMID 20671959, 2010). "This was further confirmed by a strong therapeutic effect of adenoviral-derived inhibitory motifs in different colitis models, including chronic DSS-induced colitis, the T cell-dependent SCID transfer model of colitis, and IL-10-deficient mice, which develop spontaneous colitis." (PMID 21188217, 2010). "In addition to the differential impact of bacteria on colitis in IL-10−/− mice, the onset of disease is also selectively modulated by colitogenic bacteria." (PMID 19841748, 2009). "Furthermore, VSL#3 was shown to induce protective heat-shock-proteins in intestinal epithelial cells (IEC) or proliferation of IL-10-dependent TGFβ-bearing regulatory T-cells in Th1-dependent murine colitis." (PMID 19197385, 2009). "Consistent with the finding that injection of an anti-IP-10 antibody leads to the attenuation of colitis in IL-10−/− mice, our study revealed that the post-transcriptional inhibition of IP-10 secretion in cecal epithelial cells by VSL#3 is paralleled by reduced cecal inflammation." (PMID 19197385, 2009). "More specifically, it has been shown that IL-10 produced by Treg cells is essential for in vivo suppression, as IL-10-deficient Treg cells can not regulate T cell induced colitis." (PMID 19852824, 2009). "IL-10 deficient mice develop spontaneous colitis due to immune imbalance and lack of negative regulation." (PMID 19172487, 2009). "This work suggests that increased intestinal permeability may be an important aetiological event in the development of colitis in IL10−/− mice." (PMID 18829978, 2009). "Interestingly, although we previously showed that Bay 11-7085 attenuated commensal bacteria-induced colitis in IL-10−/− mice, histological analysis showed that C. jejuni-induced colitis still developed in mice treated with the NF-κB inhibitor (data not shown)." (PMID 19841748, 2009). "Indeed, although dss-induced intestinal injury is worsened in Myd88−/− mice, spontaneous colitis observed in Il10−/− mice is attenuated in Il10−/−; Myd88−/− mice 17,18." (PMID 19672421, 2009). "Furthermore, the effect of VSL#3 on TNF-induced ileitis in heterozygous TNFΔARE mice and on colitis in IL-10−/− mice was investigated in the context of IP-10 expression in IEC." (PMID 19197385, 2009). "Indeed, persistent presentation of flora present in conventional housing is required for colitis in IL-10-/- B6 mice." (PMID 18533024, 2008). "We illustrate several cellular mechanisms that may drive Mycobacteria-enhanced colitis in IL-10-/- mice." (PMID 18533024, 2008). "Similarly, anti-IL-17 treatment had little impact on the T cell-mediated colitis that develops in IL-10-deficient mice or in RAG-deficient recipients of IL-10-deficient CD4+ T cells, although the colitis was dependant on IL-23." (PMID 18400195, 2008). "The effect of LMP-420 was additionally studied in the IL-10-/- model of murine colitis." (PMID 18331642, 2008). "Thus, the potent down-regulation of peripheral and also mucosal TNF-α and IL-10 secretion by Gal-4 underscores the potential therapeutic use of Gal-4 and explains its beneficial effect in experimental colitis." (PMID 18612433, 2008). "Presumably, IL-10 deficiency or a host that elicits Th1-biased immune responses to microbial challenge supports the development of colitis with either undetectable or no growth of M. avium paratuberculosis." (PMID 18533024, 2008). "Mycobacteria-challenged IL-10-/- mice housed under otherwise pathogen-free conditions develop colitis that is driven by CXCR3- and corresponding ligand(s)-expressing leukocytes, which underscores another important hallmark or molecule mechanism of colitis." (PMID 18533024, 2008).
colitis (continued). "Colitis has been reported to develop spontaneously in IL-10-deficient mice that are not kept germ-free, but the age of onset can vary widely between animal facilities." (PMID 18331642, 2008). "Despite the significant increase in SAA and more pronounced reduction in body mass, both live and heat-killed Mycobateria challenged IL-10-/- mice developed histologically similar colitis than compared to controls, as illustrated by significantly higher colitis disease scores." (PMID 18533024, 2008). "Interestingly, NF-κBEGFP transgenic mice exposed to luteolin showed worse DSS-induced colitis (weight loss, histological scores) compared to control-fed mice, whereas spontaneous colitis in IL-10−/−;NF-κBEGFP mice was significantly attenuated." (PMID 17611628, 2007). "IL-10 treatment can reduce inflammation in several models of colitis and human IBD." (PMID 16259632, 2005). "Furthermore the efficacy of IL-10 administration in mouse colitis models is variable and model-specific." (PMID 16259632, 2005). "Second, the DSS-induced colitis model only partially recapitulates the complex pathophysiology of human inflammatory bowel disease, underscoring the need for future validation using spontaneous models such as IL-10 knockout mice and human intestinal organoid systems." (PMID 41550498, 2026). "lactis 832 treatment significantly alleviated colitis severity (p < 0.05), as evidenced by reduced weight loss, disease activity index (DAI), and colonic injury, accompanied by significantly decreased pro-inflammatory cytokine expression and increased Il10 expression (p < 0.05)." (PMID 42197475, 2026). "IL-10 may regulate intestinal permeability through the claudin/claudin receptor pathway and TNF-α-related mechanisms, and inhibition of this pathway has been shown to improve permeability and reduce the risk of colitis in IL-10-deficient mice." (PMID 40370438, 2025). "However, another Seres product, SER−301, a defined microbial community of a consortium of 18 strains, has shown positive preclinical testing with animal models, reporting robust modulation of colonic CD4+ T cells in DSS-induced colitis mice and attenuation of intestinal inflammation in IL10-/- mice." (PMID 41239968, 2025). "Furthermore, targeted delivery of IL-10 reduced colitis by reducing inflammatory cytokines." (PMID 39990215, 2025). "Tregs are pivotal for maintaining intestinal immune equilibrium, demonstrated by their capacity to prevent or treat experimental colitis in adoptive transfer models and by the spontaneous colitis that develops in IL‐10‐deficient mice lacking functional Treg populations." (PMID 41473023, 2025). "In addition, the expression levels of the anti-inflammatory IL-10 and IL-22 in the DSS + GMEVs group were considerably greater than in the DSS group, with this difference perhaps underlying the beneficial effect of GMEV pre-treatment for relieving colitis." (PMID 40361597, 2025). "Thus, the intestinal circadian clock is disrupted in IL-10 deficient mice, including asymptomatic mice that have not yet developed experimental colitis, suggesting a link between the susceptibility to colitis and the circadian clock in this model." (PMID 39843997, 2025). "This indicates eosinophils may not have a primary pathogenic role in IL-10 deficiency-driven colitis." (PMID 40860650, 2025). "Furthermore, induced IL-10 deficiency in Treg cells did not further exacerbate weight loss in the DSS-induced colitis model compared to identically treated littermate controls." (PMID 39905200, 2025). "The content of IL-10 in culture supernatant was measured by an enzyme-linked immunosorbent assay (ELISA), and CD4+Foxp3+ Treg cells were sorted and adoptively transferred (40,000 cells/mouse) via tail vein injection into C57BL/6 J mice, followed by DSS administration to induce acute colitis." (PMID 40597393, 2025).
colitis (continued). "Similarly, preclinical studies on inflammatory bowel disease (IBD) highlight the ability of MSCs to modulate immune responses; MSC treatment reduces colitis severity by inducing macrophage polarization toward an anti-inflammatory state through the secretion of interleukin-10 (IL-10)." (PMID 40809065, 2025). "The crucial role of IL-10 within the colonic mucosa is evidenced by infants carrying mutations in IL10 (interleukin 10), IL10RA (interleukin 10 receptor subunit alpha) or IL10RB (interleukin 10 receptor subunit beta), who develop severe colitis within the first weeks of life." (PMID 41010030, 2025). "Importantly, the fecal microbiota of IL-10-/- mice from our experiments consistently displayed distinct taxonomic compositions and an increasingly disrupted circadian compositional microbiota rhythmicity, even before the development of colitis symptoms." (PMID 39843997, 2025). "Additionally, NK1R agonism may play a role in augmenting T cell cytokine production, as in T cells isolated from IL-10 knockout mice with NSAID-induced colitis, TGF-β and SP were required for upregulated production of IL-17 and IFN-γ." (PMID 38221552, 2024). "Since mouse-adaptation of human microbiota in the non-inflamed (WT) host reduced the frequency of pathobionts while expanding putatively protective bacteria, we investigated whether NIMM-g1 induces less severe colitis than IMM-g1 when transplanted to Il-10−/− GF mice." (PMID 39113097, 2024). "However, IL-10−/−IL-27rα−/− mice had mild crypt elongation and reduced expression of the pro-inflammatory cytokines, suggesting that IL-27 may promote colitis development." (PMID 38566992, 2024). "The different outcomes of these prior colitis studies compared to ours may reflect pathophysiological differences between IL-10−/− colitis and the two chemically-induced colitis models, the distinct routes of PM exposure (oral vs. inhalation), and different particle source and size distribution." (PMID 39000289, 2024). "IL-23 production by cDCs may be protective in acute colitis models such as DSS-induced colitis, whereas IL-23 upregulation by CX3CR1+ macrophages exacerbates chronic colitis models, including those induced by IL-10 deficiency or anti-CD40 agonistic antibody injection." (PMID 39379604, 2024). "Indeed, a high IL-10/IL-12 score was previously associated with the ability of LAB strains to suppress immune responses in cell models, even in absence of pro-inflammatory stimulus, as well as in colitis models, in vivo." (PMID 37202651, 2024). "In DSS-induced colitis, specifically, immunocyte dysfunction leads to abnormal secretion levels of pro-inflammatory cytokines such as tumor necrosis factor-alpha, interleukin-1β, and IL-6, while anti-inflammatory cytokines like IL-10 secretion decrease (p < 0.01)." (PMID 38612465, 2024). "Notably, pure IL-10 deficiency results in a different phenotype with predominantly colitis and no predisposition to S. aureus infection or changes in lung structure." (PMID 37982695, 2024). "As a separate test of the protective role for mucus in this colitis model, which could potentially be influenced by the presence of dietary fiber independently of bacteria, we bred Il10−/−Muc2−/− double knockout (DKO) germfree mice, colonized them with the SM14 and fed either the FR or FF diets." (PMID 36993463, 2023). "Also, after NOD2 was deleted in IL-10−/− mice, the symptoms of colitis were significantly improved." (PMID 37833958, 2023). "In contrast to the direct in vitro suppression of IL-10 expression by tofacitinib, however, the number of IL-10+ CD4+ T cells in colitis mice on day 90 could not only be reverted by the late administration of tofacitinib but also sometimes even exceeded the levels observed in control mice." (PMID 37275854, 2023). "Since IL-10-producing B cells (B10) suppress experimental arthritis in a CD1d-dependent manner, it will be interesting to investigate whether iNKT cells cross-talk with B10 cells to regulate colitis." (PMID 38274786, 2023).
colitis (continued). "In addition, Qing Dai and indigo may improve colitis by activating AHR to upregulate IL-10 and IL-22." (PMID 37179416, 2023). "Relevant to the IL-10−/− model, colitis is abrogated in germ-free conditions and ameliorated by changing the balance of intestinal flora, which may be related to the requirement of MMTV to use bacterial LPS to cross the mucosal barrier and gain access to the Peyer’s patches." (PMID 36869359, 2023). "Furthermore, IL-10 and its receptor prevent spontaneous colitis development." (PMID 37569708, 2023). "using antigen-activated CD4+ T cells cultured in the presence of IL-10 led to the identification of a distinct T cell subset, thereafter named TR1, that could prevent the development of experimental colitis in an IL-10- and transforming growth factor beta (TGFβ)-dependent manner." (PMID 37818381, 2023). "In a colitis-associated colon cancer mouse model, L. bulgaricus decreased intestinal inflammation and reduced tumour levels of IL-1β, IL-6, IL-17, IL-23 and TNF-α; L. acidophilus, L. rhamnosus and B. bifidum also reduced TNF-α and increased IL-10 in the colon of this mouse type." (PMID 35408849, 2022). "In addition, healthy donor (HD) bacteria significantly reduced the levels of inflammatory markers Myeloperoxidase (MPO) and Eosinophil peroxidase (EPO), and various pro-inflammatory factors, in colitis mice, and increased the secretion of the anti-inflammatory factor IL-10." (PMID 35237276, 2022). "However, A. muciniphila has also been reported to induce colitis in germ-free IL10-deficient mice, indicating that A. muciniphila is not an elixir for IBD under all circumstances." (PMID 36685588, 2022). "Interestingly, IL-23 deficiency (IL-12p19−/−), but not IL-12 deficiency (IL-12p35−/−), abrogated spontaneous colitis in IL-10−/− mice." (PMID 36012618, 2022). "Furthermore, although the development of colitis in IL-10−/− mice led to baseline taxa redistribution, as compared with noninflamed littermates, both β7 and IgA deficiency resulted in additional changes in taxa, which were clearly distinct from inflamed and noninflamed mice." (PMID 34433904, 2022). "Although infection with Helicobacter species was found to drive enterocolitis in IL-10-deficient mice, adult germfree IL-10-deficient mice in a specific pathogen-free (SPF) environment lacking Helicobacter developed more severe colitis when compared to IL-10-deficient mice colonised at weaning." (PMID 36012618, 2022). "Taken together, these results suggest that Se-SDF could inhibit the pathogenesis of colitis in mice by promoting the release of anti-inflammatory cytokines (IL-10 in male and female mice) and suppressing pro-inflammatory cytokines (TNF-α and IL-6 in female mice, TNF-α in male mice)." (PMID 36159466, 2022). "Previous studies have showed that wogonin can be used to treat colitis by inducing the expression of transcription factor HIF-1α through the protein kinase B/glycogen synthase kinase β (AKT/GSK3β) signaling pathway to increase interleukin 10 (IL-10) production." (PMID 35399629, 2022). "Concerning IL-10, it is possible to confirm that the treatment with hemin had a positive influence on decreasing the levels of this anti-inflammatory cytokine in both dosages in comparison to the TNBS group, demonstrating that hemin is beneficial in the inflammatory response caused by colitis." (PMID 36009572, 2022). "Regarding IL-10, the TNBS group presented the highest value among all groups, which may be linked to the adaptation of the immune system to chronic inflammation of colitis, which results in a greater production of this anti-inflammatory cytokine to combat the disease." (PMID 36012393, 2022). "In addition, IL-10/IL-22 double-deficient mice lacking colitis exhibited higher microbial diversity when compared to IL-10-deficient mice." (PMID 36012618, 2022). "Importantly, the amelioration of the severity of experimental colitis was IL-10 dependent." (PMID 35626660, 2022).